KCNJ5 (potassium inwardly rectifying channel subfamily J member 5)
Diseases named in the same sentence as KCNJ5 in open-access papers (continued):
Sharing a sentence is not in itself a finding about the gene and the disease.
primary aldosteronism (24 papers, 2012 to 2025). An endocrine disorder characterized by excessive production of aldosterone by the adrenal glands. "Following this, we discuss the clinical implications of KCNJ5 mutations to support better cardiovascular outcomes of primary aldosteronism." (PMID 36012306, 2022). "Somatic KCNJ5 mutation occurs in half of unilateral primary aldosteronism (PA) and is associated with more severe phenotype." (PMID 33995277, 2021). "Many aldosterone-producing adenomas (APA) have mutations in KCNJ5 that cause primary aldosteronism and make cells hyperresponsive to ACTH." (PMID 34572026, 2021). "Studies on excised adrenals from primary aldosteronism patients have found that somatic mutations in KCNJ5 frequently cause excess aldosterone production in the culprit aldosterone-producing adenoma (APA)." (PMID 31636604, 2019). "Germline KCNJ5 mutations (G151R, G151E and T158A) were also reported to cause a rare dominant form of primary aldosteronism, Familial hyperaldosteronism type III." (PMID 22848660, 2012). "There are many reports of potassium channel KCNJ-5 mutation in primary aldosteronism." (PMID 39596027, 2024). "Additionally, we applied PE to generate porcine blastocysts with a biomedically relevant point mutation (KCNJ5 p.G151R) as a porcine model of human primary aldosteronism." (PMID 37308830, 2023). "In addition, laboratory findings of primary aldosteronism (PA) were significantly correlated with p21 status in KCNJ5-mutated tumors." (PMID 34070051, 2021). "Another study on patients with primary aldosteronism uncovered that KCNJ5 mutations were associated with higher baseline PHQ scores and a better response to treatment with adrenalectomy, indicating that KCNJ5 mutations may participate in the formation of depressive symptoms." (PMID 39416947, 2024). "Mutations in the KCNJ5 gene, which encodes G protein-activated inward rectifier potassium (K+) channel 4 (GIRK4), are associated with the development of primary aldosteronism." (PMID 39765659, 2024). "Multicenter studies have reported that the most frequent genetic abnormalities are KCNJ5 somatic mutations, which were found in approximately 40% of aldosterone-producing adenoma (APA), a subtype of primary aldosteronism." (PMID 33986730, 2021). "Several studies have confirmed the tumorigenic role of this mutation as it was mutually exclusive to ion channel-related (KCNJ5, ATP1A1, ATP2B3, and CACNA1D) mutations in primary aldosteronism." (PMID 29594118, 2018). "The coding region and flanking intronic segments of KCNJ5 were subjected to Sanger DNA sequencing in 351 aldosterone producing lesions, from patients with primary aldosteronism and 130 other adrenocortical lesions." (PMID 22848660, 2012). "Characteristics of 56 nodules with and without KCNJ5 mutations in 24 patients with primary aldosteronism (PA)." (PMID 35492351, 2022). "The discovery of the KCNJ5 somatic mutation in aldosteroene producing adenoma (APA) in 2011 and the development of specific CYP11B2 antibodies in 2012 have greatly advanced our understanding of the pathophysiology of primary aldosteronism." (PMID 36012306, 2022). "Indeed, a proportion of patients with primary aldosteronism are now known to harbor adrenal cortical adenomas with heterogeneous molecular alterations (KCNJ5, ATP1A1, ATP2B3, and CACNA1D) involving the calcium/calmodulin kinase signaling pathway." (PMID 29594118, 2018). "Furthermore, combining this mass spectrometry-based plasma steroid profiling with machine learning enabled the diagnosis of the presence of primary aldosteronism and APA with KCNJ5 mutations with sensitivity of 69% and 85%, and specificity of 85% and 97%, respectively." (PMID 36012306, 2022).
hyperaldosteronism (13 papers, 2012 to 2025). Overproduction of aldosterone by the adrenal glands, which may lead to hypokalemia and/or hypernatremia. "In APA patients with KCNJ5 mutations, the symptoms of hyperaldosteronism are particularly severe; PA occurs in the younger age and is associated with severe HT, aldosterone secretion is much higher, and K + concentration is significantly reduced." (PMID 34829937, 2021). "The recent discovery of the KCNJ5 mutation as the etiology of FA type III has allowed understanding of the pathomechanism of hyperaldosteronism in this disease." (PMID 34829937, 2021). "Interest in the role of the GIRK4 K channel in controlling adrenal aldosterone production has emerged only in the last few years with the discovery that both germline and somatic mutants in the KCNJ5 gene cause hyperaldosteronism." (PMID 29222092, 2018). "The present study supported the possible association between the presence of somatic KCNJ5 mutations and early detection of hyperaldosteronism because of a more severe APA phenotype." (PMID 26807823, 2016). "In addition to GRA, other inherited forms exist, including a recently described family with mutations in the KCNJ5 gene, which leads to massive bilateral adrenal hyperplasia and severe hyperaldosteronism." (PMID 23110780, 2012). "KCNJ5 mutations cause more marked hyperaldosteronism, combination of another two studies, KCNJ5-mutated patients suffer from more cardiovascular complications than KCNJ5 nonmutated ones." (PMID 25906099, 2015). "The association of female sex with macro-APAs and with increasing plasma aldosterone concentrations is consistent with a meta-analysis report of patients with KCNJ5-mutated APAs displaying larger tumours and more pronounced hyperaldosteronism compared with patients with APAs without KCNJ5 mutations." (PMID 30654107, 2019).
atrial fibrillation (12 papers, 2017 to 2025). A disorder characterized by an electrocardiographic finding of a supraventricular arrhythmia characterized by the replacement of consistent P waves by rapid oscillations or fibrillatory waves that vary in size, shape and timing and are accompanied by an irregular ventricular response. "Human variants in KCNJ5 have been identified in familial hyperaldosteronism type III, long QT syndrome, atrial fibrillation, and sinus node dysfunction." (PMID 37446026, 2023). "This review will discuss the role of inherited KCNJ5 variants in familial hyperaldosteronism type III and long QT syndrome and explore the relevance of KCNJ5 in both atrial fibrillation (AF) and sinus node dysfunction (SND)." (PMID 37446026, 2023). "These included channel subunits previously linked to atrial fibrillation, including SCN3B and SCN4B41, which were more highly expressed in the LA, and KCNJ5 and HCN441, which were more highly expressed in the RA." (PMID 30224797, 2018). "This extended gene network contained a number of transcription factors (Tbx5, Hand2, Fhl2, and Gata4) and ion/calcium handling genes (Ank2, Cacna2d2, Scn5a, Kcnd2, Kcnj5, Myoz2, Casq2, Csrp3, and Gja3) of interest in the context of atrial fibrillation." (PMID 28720711, 2017).
adrenal adenoma (10 papers, 2018 to 2025). "In our case, we identified a novel somatic KCNJ5 c.503T > G mutation in the left adrenocortical adenoma." (PMID 36960396, 2023). "A KCNJ5 157-159delITE mutation in an adrenal adenoma was identified among 228 DNA samples extracted from APA tumoral tissues." (PMID 34440230, 2021). "In the present case, we detected a pathogenic variant in KCNJ5 in the adrenocortical adenoma." (PMID 39027636, 2024). "The heterogeneity of the tumor cell compositions of A/CPAs and somatic mutation of KCNJ5 may have led to different hormone secretions in the bilateral adrenal adenomas." (PMID 36960396, 2023). "Further investigation revealed that both diseases were caused by KCNJ5 and PRKACA mutations found in the bilateral adrenal adenomas." (PMID 39375255, 2025). "Somatic mutations of CACNA1D are among the most frequent mutations in aldosterone-producing adrenocortical adenomas, particularly in the absence of KCNJ5 mutations, where the gain of function of Cav1.3 is responsible for aldosterone production." (PMID 40540150, 2025). "A novel somatic heterozygous missense variant, KCNJ5 c.503T > G (p.L168R), was detected in the left adrenal adenoma, whereas no germline and somatic variants associated with PA and CS were found in the peripheral blood samples or right adrenocortical adenoma." (PMID 36960396, 2023). "A novel somatic heterozygous missense variant—KCNJ5 c.503T > G (p.L168R)—was detected in the left adrenal adenoma, but no other causative variants associated with PA and CS were detected in the peripheral blood or right adrenocortical adenoma." (PMID 36960396, 2023). "Sanger sequencing of KCNJ5 was performed on DNA extracted from adrenal adenoma." (PMID 35444613, 2022). "Transcriptome and immunohistochemical analysis showed that Na/K-ATPase (NKA) expressions in ATP1A1 mutated APA were more abundant than those in non-functioning adrenocortical adenoma or KCNJ5 mutated APAs." (PMID 34681640, 2021). "Based on the results of immunohistochemistry in the present case and the previous study, some adrenocortical adenomas with pathogenic variants in KCNJ5 may not be in charge of the lesion." (PMID 39027636, 2024). "The right adrenal adenoma showed CYP11B1-negative and CYP11B2-positive staining and harbored the KCNJ5-L168R mutation." (PMID 35399924, 2022).
adrenal tumor (9 papers, 2017 to 2025). "Presently, the identification of KCNJ5 mutations requires adrenalectomy and sampling of adrenal tumor tissues for Sanger sequencing." (PMID 37614534, 2023). "We sequenced the DNA extracted from her adrenal tumor and peripheral whole blood and concluded that there was a somatic mutation KCNJ5 157-159delITE in this patient." (PMID 34440230, 2021). "In APA patient with KCNJ5 mutations, opened calcium channels and the overexpression of CYP11B2 lead to excessive aldosterone secretion from the adrenal tumor." (PMID 35311227, 2022). "Somatic KCNJ5 mutation (Leu168Arg) was found in the right adrenal tumor, and there was no KCNJ5 mutation in the left adrenal tumor." (PMID 32075693, 2020). "Somatic KCNJ5 mutation (Leu168Arg) was found in the right tumor; there was no KCNJ5 mutation in the left adrenal tumor." (PMID 32075693, 2020).
adrenal hyperplasia (7 papers, 2012 to 2022). "Germline mutations in KCNJ5 G151R and T158A cause massive adrenal hyperplasia on CT scan whereas another mutation in KCNJ5 G151E shows minimal hyperplasia." (PMID 35757409, 2022). "With some exceptions, KCNJ5 mutations that are also found in APAs, when present in the germline, appear to be associated with the development of macroscopic adrenal hyperplasia and a severe phenotype." (PMID 31695023, 2019). "A proliferative effect of KCNJ5 mutations is also suggested by the peculiar case of a patient with germline mosaicism in whom adrenal hyperplasia was restricted to those areas of the adrenal gland that carried KCNJ5 mutations." (PMID 31695023, 2019). "Mutations in the KCNJ5 gene can produce increased Na+ conductance in a mendelian form of severe aldosteronism and massive bilateral adrenal hyperplasia." (PMID 24376526, 2013). "Additional support for the notion that KCNJ5 mutations are sufficient to cause aldosterone production and proliferation came from the discovery of heterozygous germ line KCNJ5 mutations in families with early-onset PA and massive bilateral adrenal hyperplasia." (PMID 27445978, 2016).
Arrhythmia (6 papers, 2018 to 2024). Any cardiac rhythm other than the normal sinus rhythm. "Together with our findings that miR-221/222 reduce Kcnj5 current and L-type Ca2+-current in vitro, which are elevated in the same mouse model, this could be an interesting mechanism involved in cardiac arrhythmia." (PMID 34201741, 2021).
familial hyperaldosteronism (6 papers, 2019 to 2024). "Genetic causes of familial hyperaldosteronism have been expanded through the report of germline pathogenic variants in KCNJ5, CACNA1H and CLCN2 genes." (PMID 35813615, 2022). "Somatic mutations in four genes (KCNJ5, ATP1A1, ATP2B3 and CACNA1D) have been identified in nearly 60% of the sporadic APAs, while germline mutations in KCNJ5 and CACNA1H have been reported in different subtypes of familial hyperaldosteronism." (PMID 34829937, 2021). "Rare germline variants of CYP11B2 (encoding aldosterone synthase), CLCN2 (encoding voltage-gated chloride channel ClC-2), KCNJ5, CACNA1H (encoding a subunit of T-type voltage-gated calcium channel CaV3.2), and CACNA1D have been reported in different subtypes of familial hyperaldosteronism." (PMID 31695023, 2019).
familial hyperaldosteronism type III (6 papers, 2015 to 2026). "Congenital hyperaldosteronism caused by variation in the KCNJ5 gene is classified as familial hyperaldosteronism type III." (PMID 37446026, 2023). "KCNJ5 mutation is related to the pathogenesis of sporadic and familial PA, and familial hyperaldosteronism type III could be excluded by KCNJ5 gene detection." (PMID 38965078, 2024). "Of these, type 3 familial hyperaldosteronism is associated with germline KCNJ5 mutations; therefore, a small proportion of seemingly sporadic aldosterone-producing adenomas with KCNJ5 mutations may in fact be a harbinger of this condition." (PMID 29594118, 2018). "Germline KCNJ5 mutations were also identified as the causative event of Familial hyperaldosteronism type III (FH-III)." (PMID 26124749, 2015).
hypercortisolism (6 papers, 2018 to 2022). "Third, in another recent study by our group, we found that the presence of KCNJ5 mutations was associated with a lower incidence of subclinical hypercortisolism." (PMID 34503121, 2021). "Subclinical hypercortisolism is sometimes accompanied by APA; aldosterone and cortisol co-producing adenoma has also been reported in KCNJ5-mutated APA." (PMID 33920271, 2021). "A recent study based on a Taiwanese database showed that the presence of KCNJ5 mutations was significantly lower among APA patients with subclinical hypercortisolemia than those without." (PMID 33796078, 2021). "However, a recent prospective study showed that subclinical hypercortisolism was common in APA without KCNJ5 mutation or with a relatively larger tumor size." (PMID 33920271, 2021). "The higher incidence of subclinical hypercortisolism and subsequent comorbidity in APA patients without KCNJ5 mutations compared to those with KCNJ5 mutations may therefore also contribute to a smaller reversal in baPWV after surgery." (PMID 34503121, 2021).
Hypokalemia (6 papers, 2020 to 2026). An abnormally decreased potassium concentration in the blood. "In summary, the typical clinical characteristics of APAs harboring KCNJ5 mutations are female dominance, higher aldosterone production capacity, and induction of hypokalemia, compared with KCNJ5-wild APAs." (PMID 39877848, 2024). "It suggested that KCNJ5 mutations were more frequent in APAs with hypokalemia since all the APA patients in our study had hypokalemia." (PMID 32411097, 2020). "In our hands, most patients with APA had KCNJ5 mutation and all of them corresponding hypokalemia." (PMID 32411097, 2020). "Induced membrane depolarization, increased Ca2+ influx, increased aldosterone production; deregulated cell growth.Male dominance; size typically <20 mm (reduced APA size relative to KCNJ5 mutant APAs), high aldosterone level and hypokalemia." (PMID 41601940, 2026).
long QT syndrome (6 papers, 2013 to 2025). "The G387R KCNJ5 variant identified in Andersen–Tawil syndrome was also identified in an additional subtype of long QT syndrome, Romano–Ward syndrome (long QT 13)." (PMID 37446026, 2023). "In addition, a mutation in the human GIRK4/KCNJ5 gene underlies a congenital form of Long QT Syndrome (LQTS13), a ventricular repolarization disorder associated with arrhythmia, syncope, and sudden death." (PMID 29352184, 2018). "CALM1 and KCNJ5 have strong and limited CV scores for long QT syndrome, respectively, and LDB3 scored moderate for DCM and left ventricular non‐compaction (LVNC)." (PMID 30900393, 2019).
breast carcinoma (5 papers, 2004 to 2016). "CD79A, SERPINH1, KCNJ5 and TMEM14C exhibited breast cancer subtype–independent overall survival differences." (PMID 25572802, 2015).
metabolic syndrome (5 papers, 2017 to 2024). A cluster of metabolic risk factors for CARDIOVASCULAR DISEASES and TYPE 2 DIABETES MELLITUS. "In short, APA patients appear lean, especially those with KCNJ5 mutations, but physicians should be aware of the high risk of cardiovascular diseases related to aldosterone toxicity and worsening dyslipidemia after adrenalectomy." (PMID 36950676, 2023). "In our prior study we investigated serum CRP levels in PA patients, and showed that KCNJ5 mutations were associated with lower levels of pro-inflammation factors, metabolic syndrome and abdominal obesity." (PMID 35311227, 2022). "In the TAIPAI group, Chen et al20 evaluated the prevalence of metabolic disorders and abdominal obesity, showing that patients with uPA who harbored KCNJ5 mutations had a significantly lower prevalence of metabolic syndrome and a lower distribution of body adipose tissue." (PMID 37614534, 2023). "Before matching, KCNJ5-mutant carriers were younger (p < 0.001) and had lower prevalence of dyslipidemia (p = 0.017), than non-mutant carriers." (PMID 28415786, 2017).
Obesity (5 papers, 2019 to 2025). Accumulation of substantial excess body fat. "Blood pressure control after adrenalectomy tends to be better in women.Patients who harbour KCNJ5 mutations have better clinical outcomes after surgery.Patients who harbour CACNA1D mutations have worse clinical outcomes after surgery.Men have higher rates of obesity than women." (PMID 40296186, 2025).
Primary hyperaldosteronism (5 papers, 2016 to 2023). A form of hyperaldosteronism caused by a defect within the adrenal gland. "It is recommended to investigate the mutation in the KCNJ5 gene in order to exclude or confirm the type III subtype in children with primary hyperaldosteronism." (PMID 31666819, 2019). "While evidence has suggested a role for KCNJ5 in the pathophysiology of AF, it could be possible that KCNJ5 variants contribute to the pathogenesis of AF as a result of cardiovascular changes due to primary hyperaldosteronism." (PMID 37446026, 2023).
heart hypertrophy (4 papers, 2020 to 2022). "In a retrospective cohort study scrutinizing more than 100 patients, cardiac hypertrophy, frequently seen in PA cases, was shown to improve significantly in those who harbored KCNJ5 mutated APAs after unilateral adrenalectomy compared to those with KCNJ5 wild APAs." (PMID 36012306, 2022). "The transcription of Kcnj5, Cacnb2 and Cacna1c was reduced in the hearts of mice with severe heart hypertrophy." (PMID 34201741, 2021). "Interestingly, we already reported that Kcnj5 is a target of miR-221/222, the miR-cluster that increased the most in our model of heart hypertrophy." (PMID 34201741, 2021). "In contrast, no change in Cacna1c or Kcnj5 mRNA could be observed in mice with heart hypertrophy but without upregulation of the two miRs (isoprenaline treatment)." (PMID 31312877, 2020).